EHF (ETS homologous factor)
Description:
Transcriptional activator that may play a role in regulating epithelial cell differentiation and proliferation. May act as a repressor for a specific subset of ETS/AP-1-responsive genes and as a modulator of the nuclear response to mitogen-activated protein kinase signaling cascades. Binds to DNA sequences containing the consensus nucleotide core sequence GGAA. Involved in regulation of TNFRSF10B/DR5 expression through Ets-binding sequences on the TNFRSF10B/DR5 promoter. May contribute to development and carcinogenesis by acting as a tumor suppressor gene or anti-oncogene.
Synonyms: ESE3; ESE3B; ESEJ
Tractability: PROTAC: ubiquitination databases record sites on it.
Gene: Protein-coding gene on chromosome 11 (34,617,044 to 34,663,386, forward strand). Ensembl gene ENSG00000135373.
Subcellular location: Nucleus
Subcellular location (Human Protein Atlas): Nucleoplasm; Golgi apparatus
Gene Ontology:
Molecular function: DNA binding; DNA-binding transcription activator activity, RNA polymerase II-specific; protein binding; RNA polymerase II cis-regulatory region sequence-specific DNA binding; DNA-binding transcription factor activity, RNA polymerase II-specific; DNA-binding transcription factor activity; sequence-specific DNA binding; sequence-specific double-stranded DNA binding
Biological process: epithelial cell differentiation; positive regulation of transcription by RNA polymerase II; cell differentiation; regulation of transcription by RNA polymerase II; endothelial tube formation; positive regulation of vascular permeability; regulation of DNA-templated transcription
Cellular component: nucleoplasm; nucleus; chromatin
Genetic constraint (gnomAD): Loss-of-function variants: 14 observed, 45.28 expected, observed/expected ratio (o/e) 0.31, 90% interval 0.2 to 0.48. The upper end of that interval is the gene's LOEUF score, 0.48, which puts it in group 2 of 6, group 1 being the genes least tolerant of losing a copy. Missense variants: 280 observed, 384.74 expected, observed/expected ratio (o/e) 0.73, 90% interval 0.66 to 0.8. Synonymous variants: 134 observed, 137.31 expected, observed/expected ratio (o/e) 0.98, 90% interval 0.85 to 1.13.
Homologues: Orthologues: chimpanzee EHF (99% identical), macaque EHF (99% identical), pig EHF (95% identical), rabbit EHF (95% identical), rat Ehf (94% identical), dog EHF (94% identical), guinea pig EHF (94% identical), mouse Ehf (94% identical), tropical clawed frog ehf (70% identical), zebrafish ehf (56% identical). Paralogues in human: ELF5 (40% identical), ELF3 (39% identical), ETS1 (24% identical), ETS2 (24% identical), GABPA (22% identical), ELF2 (21% identical), ELF1 (21% identical), FLI1 (21% identical), ELF4 (20% identical), ERG (20% identical), ETV5 (20% identical), ETV6 (20% identical), and 16 more.
Diseases named in the same sentence as EHF in open-access papers:
EHF is named in the same sentence as 51 diseases in open-access papers, as found by Europe PMC text mining. Sharing a sentence is not in itself a finding about the gene and the disease. The quoted sentences say what the papers report.
prostate carcinoma (18 papers, 2010 to 2025). A carcinoma that arises from epithelial cells of the prostate gland. "For example, the loss of EHF has been found to promote epithelial-mesenchymal transition and cell migration in conditions such as prostate cancer, lung cancer, pancreatic cancer, and esophageal squamous cell carcinoma." (PMID 40046872, 2025). "The findings showed that a tumorigenic and stem-like phenotype in prostate cancer is promoted by the activation of the LIN28/let-7 axis caused by the loss of ESE3/EHF." (PMID 38612395, 2024). "EHF has been previously implicated in ovarian, gastric and prostate cancer but our findings point to cooperative roles of GRHL2 target genes including EHF and E2Fs in sustaining proliferation." (PMID 36691073, 2023). "Logistic regression analysis was applied to identify the risk of prostate cancer metastasis formation associated with the GG or the expression of EHF." (PMID 35453848, 2022). "The main aim of this study was to investigate the risk of prostate cancer metastasis formation associated with the expression of ETS homologous factor (EHF) in a cohort of bioptic samples." (PMID 35453848, 2022). "We have shown that the transcription factor ESE3/EHF is frequently downregulated in prostate cancer and its loss induces cell plasticity and acquisition of mesenchymal, stem-like and tumor-initiating properties." (PMID 33500545, 2021). "For example, loss of EHF in prostate cancer activates JAK/STAT signaling and sensitizes cells to treatment with a JAK2 inhibitor." (PMID 30200227, 2018). "Therefore, starting from these considerations, the main aim of this study was to investigate the risk of prostate cancer metastasis formation associated with the expression of EHF in a cohort of bioptic samples." (PMID 35453848, 2022). "Logistic regression analysis associated the EHF expression in primary prostate cancer with a risk of developing metastatic lesions within 5 years from the diagnosis, establishing a threshold value of 40% of positive cells, beyond which the risk increases 40-fold." (PMID 35453848, 2022). "In conclusion, the immunohistochemical evaluation of EHF could significantly improve the management of prostate cancer patients by optimizing the diagnostic and therapeutic health procedures and, more important, ameliorating the patient’s quality of life." (PMID 35453848, 2022). "In contrast, several studies have shown that EHF functions as a tumor suppressor gene in pancreatic and prostate cancer." (PMID 37958443, 2023). "EHF gene expression showed the same trend as the immunohistochemical data, with an increase in EHF expression in prostate metastatic lesions with respect to both prostate cancers and benign lesions." (PMID 35453848, 2022). "Remarkably, the relative risk of prostate cancer metastasis formation was exceptionally low for patients with primary lesions characterized by 30% of EHF-positive prostate cancer cells but considerably increased for value of EHF expression ≥40%." (PMID 35453848, 2022). "In this model, EHF can be considered a molecular factor capable of inhibiting the expansion of prostate cancer stem cell compartments." (PMID 35453848, 2022). "Subsequent studies demonstrated that EHF re-expression in prostate cancer cells inhibited stem like properties and promoted epithelial differentiation by repressing EMT drivers, such as TWIST1, ZEB2, NANOG and POU5F1." (PMID 30200227, 2018). "EHF has been suggested to function as an oncosuppressor in prostate cancer and esophageal squamous cell carcinoma (ESCC), and be frequently silenced by promoter methylation." (PMID 27517321, 2016). "Collectively these data support a role of IL-6 in expanding the prostate cancer stem-like phenotype and suggest that ESE3/EHF controls both basal and IL-6 induced STAT3 response." (PMID 27732936, 2016).
prostate carcinoma (continued). "EHF is a member of ETS homologus transcription factor and it was recently reported that re-expression of ESE3/EHF inhibited tumorigenic potential of prostate cancer, while MMP1 a cell surface metallopeptidase is a miR-221/222 and miR-1928 families target." (PMID 23479461, 2013). "In addition, in prostate cancer, EHF binds to the EBS in the promoter region of IL-6 and represses its transcription, resulting in STAT3 inactivation." (PMID 37958443, 2023). "The EHF expression was also investigated in prostate cancer." (PMID 35453848, 2022). "EHF has been demonstrated to be a potential tumor-suppressor in prostate cancer and ESCC,19, 22, 23 whereas our data suggest that EHF may be a functional oncogene in gastric cancer." (PMID 27787520, 2016). "E26 transformation-specific (ETS) transcription factor EHF plays a tumor suppressor role in prostate cancer and esophageal squamous cell carcinoma (ESCC), whereas it is overexpressed and may act as an oncogene in ovarian and mammary cancers." (PMID 27517321, 2016). "However, to the best of our knowledge, no studies have been performed about the risk of prostate cancer metastasis formation related to EHF expression." (PMID 35453848, 2022). "To determine whether the link between ESE3/EHF and IL-6 observed in our cell line models was seen also in clinical samples, we analyzed gene expression data from two large (n = 545 and n = 131, respectively) human prostate cancer patients datasets." (PMID 27732936, 2016). "They found links between the LIN28/let-7 microRNA axis, the CSC subpopulation in prostate cancer, and the ETS transcription factor ESE3/EHF." (PMID 38612395, 2024). "On the other hand, ESE3/EHF was repressed in cancer cells, which led to a rise of LIN28B protein levels and was crucial for cell transformation and expansion of prostate cancer stem cells." (PMID 37304235, 2023). "However, the molecular mechanisms responsible for the EHF-mediated inhibition of the STAT3 pathway in TNBC cells might be different from those in prostate cancer cells because the mRNA level of IL-6 was significantly increased by EHF overexpression in MDA-MB-453 cells." (PMID 37958443, 2023). "Data here reported EHF as a candidate for an immunohistochemical prognostic biomarker for prostate cancer metastasis formation, regardless of the GG." (PMID 35453848, 2022). "Data here reported EHF as a candidate immunohistochemical prognostic biomarker for prostate cancer metastasis formation regardless of the Gleason scoring system." (PMID 35453848, 2022). "As target gene of BRG1, EHF has been shown to contribute to differentiation and proliferation of epithelial cells, as well as EZH2 expression, and apoptotic signaling regulation in prostate cancer stem cells." (PMID 33070167, 2020). "Interestingly, we found that ESE3/EHF, along with ERG, was one of the most frequently deregulated ETS factors in human prostate cancer." (PMID 31143708, 2019). "The previous studies have indicated that EHF acts as an oncosuppressor in prostate cancer and ESCC, whereas our data suggest that EHF may have a putative oncogenic function in thyroid cancer." (PMID 27517321, 2016). "This evidence allows speculation that EHF expression could be a prognostic factor regardless of GG, also suggesting that specific molecular signatures can explain the different metastatic potential of prostate cancer lesions with similar morphological aspects." (PMID 35453848, 2022). "Although the low number of metastatic prostate cancer data collected in NCBI-GEO dataset does not allow conclusive considerations, an increase in the EHF gene expression was also observed in the metastatic cancers if compared with tumour ones." (PMID 35453848, 2022).
breast cancer (12 papers, 2012 to 2024). A primary or metastatic malignant neoplasm involving the breast. "In this study, we identified an EHF mutation that lies in the ESE domain (L285P) in breast cancer cells, which corresponds to the L329P mutation in ELF3 in bladder carcinoma." (PMID 33712555, 2021). "The luminal-specific TF EHF is a target of GRHL2 that is conserved in luminal breast cancer cell lines." (PMID 39545637, 2024). "We also identified the epithelial cell specific Ets family transcription factor EHF as a novel AR-GATA3 target gene in breast cancer cells." (PMID 38317241, 2024). "N-myc downstream-regulated gene 2 (NDRG2) is a tumor suppressor in breast cancer, and its expression is positively correlated with ETS homologous factor (EHF) expression." (PMID 37958443, 2023). "The analysis of the TCGA dataset also showed that the expression of NDRG2 and EHF in breast cancer patients was positively correlated in the basal subtype." (PMID 37958443, 2023). "EHF was identified as a GRHL2 target harboring a GRHL2 binding site in its promoter region that was conserved in all three luminal breast cancer cell lines." (PMID 36691073, 2023). "The overexpression and knockdown of the EHF gene in human and mouse breast cancer cells were performed, and the TCGA dataset and Q-omics were analyzed." (PMID 37958443, 2023). "When we generated EHF cDNAs using mRNAs isolated from breast cancer cells by RT-PCR in this study, we found that a leucine residue at 285 in EHF was mutated to proline (L285P) in several plasmid clones purified from bacteria." (PMID 33712555, 2021). "When we isolated EHF cDNAs from mRNAs of breast cancer cells, we accidentally found that a leucine residue at 285 in EHF was mutated to proline (L285P) in several clones." (PMID 33712555, 2021). "EHF (epithelium-specific Ets transcription factor 3) is a nuclear transcription factor involved in breast cancer tumorigenesis and is a marker for poor survival in ovarian carcinoma." (PMID 23213280, 2012). "In addition, the high expression of EHF in breast cancer patients receiving chemotherapy showed prolonged relapse-free survival." (PMID 37958443, 2023). "Accordingly, we further investigated the functional role of EHF in breast cancer progression." (PMID 37958443, 2023). "Accordingly, we investigated whether the EHF expression is correlated with the suppression of the STAT3 signaling pathway in breast cancer cells." (PMID 37958443, 2023). "Epithelial markers (e.g., GRHL2, CLDN4 and E-cadherin) are lost in basal B breast cancer cells as compared to the luminal and basal A subtype and we examined whether EHF expression followed this pattern." (PMID 36691073, 2023). "Indeed, RNA-seq data from a panel of 52 human breast cancer cell lines showed a decrease of EHF RNA levels in the basal B subtype." (PMID 36691073, 2023). "Although EHF overexpression has been reported in different cancers, including gastric, ovarian and mammary cancers, the role and mechanisms of EHF in thyroid tumorigenesis remain totally unknown." (PMID 27517321, 2016). "Hence, AR-GATA3 mediated up-regulation of EHF in breast cancer cells may play a key role in mediating the tumor suppressor activity associated with AR signaling." (PMID 38317241, 2024). "In clinical datasets, high expression of KDM4B, but not EHF (data not shown), was associated with better patient outcomes, although EHF is one of 142 genes comprising a gene signature of AR activity that is prognostic in ER+ breast cancer." (PMID 38317241, 2024). "Therefore, EHF may be a novel tumor suppressor gene that acts by inducing senescence in breast cancer." (PMID 37958443, 2023). "Nonetheless, three genes (CNTNAP2, EHF, KDM4B) were significantly upregulated by DHT in all four models of breast cancer and displayed enrichment of AR, GATA3, and H3K27ac ChIP-seq signals at associated genomic loci." (PMID 38317241, 2024). "However, the functional role of EHF in breast cancer remains unclear." (PMID 37958443, 2023).
breast cancer (continued). "In the current study, we investigated the tumor suppressive role of EHF, which is thought to inhibit migration and invasion through the induction of senescence and the inhibition of the STAT3 signaling pathway in breast cancer cells." (PMID 37958443, 2023). "Collectively, these results suggest that, in TNBC cells, the EHF expression is strongly correlated with NDRG2 expression, which suppresses breast cancer progression." (PMID 37958443, 2023). "To evaluate the effect of EHF on the prognosis of breast cancer patients, we analyzed the survival rate of TNBC patients according to EHF expression using Kaplan–Meier plotter." (PMID 37958443, 2023). "The precise mechanism by which EHF regulates cellular senescence and p21WAF1/CIP1 in breast cancer needs to be investigated." (PMID 37958443, 2023). "In addition, the heatmap expression data from breast cancer patient biopsies showed that most of the NDRG2 and EHF expression levels were positively correlated." (PMID 37958443, 2023). "Studies have also demonstrated that knockdown of vimentin resulted in downregulation of genes involved in breast cancer invasion and the basal-like phenotype, including Axl, ITGB4, and PLAU, with a subsequent upregulation in the genes abundant in normal mammary epithelium, including RAB25 and EHF." (PMID 34769002, 2021). "However, the expression of EHF is not correlated with that of Snail in OSCC and breast cancer cells." (PMID 35451213, 2022).
ovarian carcinoma (10 papers, 2012 to 2025). A malignant neoplasm originating from the surface ovarian epithelium. "In contrast, high EHF expression in patients with ovarian cancer was associated with poor prognosis, and the inhibition of EHF levels significantly reduces the metastatic ability of ovarian cancer cells in vitro and in vivo." (PMID 38741887, 2024). "The knockout of EHF in ovarian cancer cells significantly inhibits cell proliferation and increases the number of G1 phase cells." (PMID 36578029, 2022). "A tumour promoting role for EHF has also been suggested in ovarian cancer (OC), where EHF mRNA is overexpressed and correlates with poor overall survival." (PMID 30200227, 2018). "Knockdown of EHF inhibited proliferation, invasion, and tumorigenesis in ovarian cancers." (PMID 30782177, 2019). "Recent studies have demonstrated that KLF5 forms a transcriptional complex with EHF and ELF3, remodeling RAD51 transcription to enhance the homologous recombination repair (HRR) pathway in ovarian cancer cells, thereby promoting ovarian cancer progression and PARPi resistance." (PMID 40307891, 2025). "Interestingly, a recent study showed that KLF5 forms a transcriptional complex with EHF and ELF3 and binds to the promoter region of RAD51 to enhance its transcription, strengthening the homologous recombination repair pathway and consequently inducing chemoresistance in ovarian cancer cells." (PMID 39865088, 2025).